ATF5 (activating transcription factor 5)
Diseases named in the same sentence as ATF5 in open-access papers (continued):
Sharing a sentence is not in itself a finding about the gene and the disease.
tumor (continued). "We then evaluated the role of ATF5 in tumor cell anchorage-independent viability and anoikis resistance, which are critical prerequisites for metastasis." (PMID 38014922, 2023). "Mechanistically, ATF5 endows tumor cells with resistance to anoikis, thereby increasing their survival in systemic circulation and facilitating metastasis." (PMID 38014922, 2023). "ATF5 knockdown inhibited tumor growth and significantly increased median survival (42 vs. 27 days, + Dox vs. −Dox, respectively, P = 0.0083)." (PMID 38014922, 2023). "ATF5 and cyclin D3 interact in those tumor cells through a positive feedback loop in which cyclin D3 enhances the ATF5 transcription." (PMID 35806136, 2022). "Accumulating evidence indicates that ATF5 regulates tumor survival and development by mediating a myriad of survival pathways, such as apoptosis, autophagy, tumorigenesis, migration, and invasion." (PMID 35806136, 2022). "Tumor formation in ATF5-overexpressing SW780 cells was markedly greater, relative to the control group." (PMID 34895217, 2021). "The assays of tumor sphere formation and tumor xenograft were further performed to assess the potential biological roles of ATF5 (activating transcription factor 5)." (PMID 34895217, 2021). "We reported that dn-ATF5 depletes survivin in multiple tumor lines and that such depletion occurs prior to and is sufficient for their death." (PMID 34065488, 2021). "The present findings establish that dn-ATF5 consistently depletes survivin expression in a wide variety of human tumor cell lines." (PMID 31551409, 2019). "Our past work has shown that CP-dn-ATF5 dramatically reduces USP9X levels in multiple tumor cell lines including T98G cells." (PMID 31551409, 2019). "To address this, we first over-expressed FLAG-survivin in T98G tumor cells and then assessed the capacity of CP-dn-ATF5 to promote their death." (PMID 31551409, 2019). "Both recombinant and synthetic forms of CP-dn-ATF5 effectively promote apoptosis of a wide variety of tumor cells in vitro and in vivo." (PMID 31551409, 2019). "Taken together, our data indicate that CP-dn-ATF5 depletes survivin levels in multiple tumor lines and appears to do so well before the appearance of cell death." (PMID 31551409, 2019). "Our past work showed that tumor cell death promoted by transfected dn-ATF5 plasmid is apoptotic in nature and is blocked by inhibition of caspase activity." (PMID 31551409, 2019). "In this study, we demonstrate that knockdown of ATF5 (ATF5-KD) in both cell lines results in a decreased tumor volume and weight, as well as in a reduced proliferation rate and migratory potential of the cells." (PMID 28785242, 2017). "Similar changes in tumor volume and weight were obtained with scrambled and ATF5-KD-shRNA#2 cells (hereafter referred to as ATF5-KD) derived from Met1 cells." (PMID 28785242, 2017). "The mice were sacrificed 16-64 hours after the last injection and the fixed brains were stained with anti-Flag antibody to detect Pen-d/n-ATF5-RP or with anti-HA to mark PDGF-B-HA expressing tumor cells, and for TUNEL to identify dying cells." (PMID 26863637, 2016). "For mice treated with Pen-d/n-ATF5-RP, MRI revealed significant reduction (2/5) or un-detectability (3/5) of tumor signals at 8 days after treatment (the earliest time monitored) and full loss of detectable tumor signal within 3 weeks (n = 7/7)." (PMID 26863637, 2016). "Furthermore, the nuclear localization of ATF5 was significantly greater in collagen-rich tumor regions, which is reported to exhibit stiffer ECMs,57,58 than collagen-poor tumor tissues which represent softer regions." (PMID 40124511, 2025). "In summary, ATF5 not only elevates the expression of antiapoptotic genes but also increases the levels of factors that regulate growth and metabolism, thereby contributing to radiotherapy resistance and promoting tumor cell invasion." (PMID 39261452, 2024). "Decreased ATF5 expression inhibits angiogenesis and tumor growth in vivo." (PMID 39261452, 2024).
tumor (continued). "We also examined the effect of ATF5 overexpression on tumor cell survival in vivo." (PMID 38014922, 2023). "Thus, the inhibition of tumor survival following ATF5 knockdown was primarily due to increased apoptosis rate." (PMID 38223508, 2023). "A critical test of this is whether interference with ATF5 expression or function inhibits tumor cell growth, survival or other aspects of malignancy." (PMID 36831248, 2023). "Similarly, anoikis of CTC was observed in mice 12 hours after ATF5 knockdown, indicating that ATF5 is a critical regulator of tumor cell survival in circulation." (PMID 38014922, 2023). "Hence, our findings established ATF5 as a tumor-specific prosurvival transcription factor, contributing to the current understanding of transcriptional dysregulation in CTCL." (PMID 38223508, 2023). "Mouse xenograft study was utilized to study the correlation of ATF5 and tumor growth in vivo." (PMID 33980247, 2021). "In past work, we characterized anti-tumor activity of a cell-penetrating dn-ATF5." (PMID 34065488, 2021). "In addition, ATF5 is characterized as an important player in the mitochondrial stress response, of relevance to tumor cell survival." (PMID 34065488, 2021). "It would be useful to investigate miR-141-3p in the context of cellular stress, which was not examined in the previous study, as well as whether miR-520b-3p suppression of ATF5 expression could also lead to decreased tumor growth." (PMID 32603335, 2020). "In this context, we thus asked whether the capacity of CP-dn-ATF5 to deplete survivin is necessary for its ability to promote tumor cell death or whether this agent also has additional death-promoting activities." (PMID 31551409, 2019). "Some of these genes are of particular interest in the context of HCC: female-biased CXCL14 and ATF5 may modulate antitumor immune responses and have a tumor suppressor role in HCC." (PMID 31615477, 2019). "We previously reported that expression of dn-ATF5-encoding plasmids promotes apoptotic death of a wide range of tumor cell types, but not of non-transformed cells." (PMID 31551409, 2019). "Is survivin depletion by CP-dn-ATF5 sufficient to account for the anti-tumor actions of this agent?" (PMID 31551409, 2019). "The mechanisms by which dn-ATF5 promotes tumor cell death are only partially understood." (PMID 31551409, 2019). "We therefore next tested whether this potential therapeutic prototype form of dn-ATF5 would also affect tumor cell survivin protein levels." (PMID 31551409, 2019). "Dn-ATF5 expression triggers extensive apoptotic death of tumor cells." (PMID 31551409, 2019). "Because dn-ATF5 depletes survivin in tumor cells, this suggests that it may also serve in combination therapies to overcome therapeutic resistance." (PMID 31551409, 2019). "In contrast, neither plasmid nor penetratin delivered dn-ATF5 appears to affect survival of non-transformed cells and there have been no evident side-effects in mice treated with either the recombinant or synthetic forms of CP-dn-ATF5 at doses that suppress tumor growth." (PMID 31551409, 2019). "Importantly, the strong 2.9-fold increase of Atf5 transcription in JPH203-treated tumors suggests that LAT1 inhibition depleted EAA concentration in tumor cells in vivo." (PMID 30241549, 2018). "Given the earlier finding of the high cellular uptake efficiency and theoutstanding endosome escape ability, we speculate that ATF5-CaP-rHDL can bedelivered to tumour cells to specifically block ATF5 gene expression,thus providing anti-tumour efficacy." (PMID 28489075, 2017). "Therefore, we next investigated the effect of ATF5 knockdown in Mvt1 and Met1 cells on tumor growth, cell proliferation, and migration and intracellular signaling pathways." (PMID 28785242, 2017). "Thus, it is possible that an increased autophagy and a reduced proliferation rate of ATF5-KD Mvt1 and Met1 cells lead to the reduced tumor growth shown in the present study." (PMID 28785242, 2017).
tumor (continued). "Co-localized TUNEL and PDGF-B-HA+ tumor marker staining continued to be evident at 64 h after Pen-d/n-ATF5-RP treatment, but the signals indicated cell degeneration and fragmentation compared with cells treated with this peptide for 16 h or with Pen-Control-RP peptide." (PMID 26863637, 2016). "Furthermore, RNAi-mediated knockdown of ATF5 induces apoptosis in a variety of tumor cell lines derived from lung, prostate, skin, and ovary." (PMID 21311102, 2010). "Additionally, the m7G modification mediated by TRMT112 could facilitate tumor development and progression through the upregulation of ATF5 transcription, thereby complicating the immunotherapy landscape." (PMID 41235342, 2025). "Furthermore, ATF5 knockdown significantly impeded tumor growth in a xenograft model using H9 cells." (PMID 38223508, 2023). "We next evaluated whether CP-d/n-ATF5 could inhibit tumor growth and metastasis in vivo." (PMID 38014922, 2023). "Patients in the ATF5-high group exhibited a tendency towards shorter progression-free survival, although the difference was not statistically significant, which could be attributed to the fact that all the patients from this cohort were in the tumor stage." (PMID 38223508, 2023). "In addition to ATF5’s carcinogenic role, it appears to suppress tumor growth in HCC." (PMID 35806136, 2022). "Thus, combining anti-IGF-I receptor and anti-ATF5 therapies may show good efficiency in attenuating aggressive CD24-positive tumor growth." (PMID 28785242, 2017). "Dpep is a cell-penetrating peptide that targets transcription factors ATF5, CEBPB and CEBPD to selectively suppress growth and survival of diverse tumor cell types in vitro and in vivo." (PMID 42121927, 2026). "AM80 treatment significantly reduced the nuclear localization of ATF5 and induced EGR1 expression in the nuclei of tumor tissues." (PMID 40124511, 2025). "Mechanistically, ATF5 promotes the transcription of disheveled-1 (DVL1), a potent activator of Wnt/β-catenin, and increases tumor sphere formation ability through the ATF5/DVL1/Wnt/β-catenin axis." (PMID 39261452, 2024). "We highlight one such strategy, namely, the design of cell-penetrating dominant-negative decoy peptides that exploit the leucine zipper properties of ATF5 and/or CEBPB and CEBPD, and that selectively suppress the growth and survival of tumor cells." (PMID 36831248, 2023). "As reviewed here, perturbation of ATF5/CEBPB/CEBPD affects a variety of properties of brain and other tumor cells such as their survival, growth, migration, mesenchymal transition, and response to therapeutics." (PMID 36831248, 2023). "ATF5 can modulate the expression of ClpP and HSP60, leading to tumor cell apoptosis and cell growth." (PMID 37095454, 2023). "Dpep is a cell-penetrating peptide targeting transcription factors ATF5, CEBPB, and CEBPD, and that selectively promotes the apoptotic death of multiple tumor cell types in vitro and in vivo." (PMID 38001578, 2023). "Further, we demonstrated that silencing ATF5 phenocopies HIF1α knockdown in tumorigenic properties in vitro and inhibited ESCA tumor angiogenesis and proliferation in vivo." (PMID 33980247, 2021). "And also the proliferation and survival of tumor cells are mediated through gene expression of Egr-1, BCL-2, and MCL1 by ATF-5." (PMID 34717757, 2021). "Statistic analysis of the 140 BLCA samples revealed that ATF5 expressions were associated with clinical grade (P = 0.034), stage (P = 0.014), tumor multiplicity (P = 0.004), recurrence (P = 0.022) as well as progression (P = 0.016), however, they were not correlated with gender, tumor size or age." (PMID 34895217, 2021). "On the basis of understanding the molecular mechanism of UPRmt, targeted downregulation of UPRmt signal molecules, including CHOP, ATF-5, and SIRT3, would retard tumor growth and induce the cell apoptosis." (PMID 34717757, 2021).
tumor (continued). "dn-ATF5 decreases levels of anti-apoptotic proteins BCL2 and MCL1 in tumor cells by what appears to be both decreased transcription and elevated protein destabilization." (PMID 31551409, 2019). "Finally, to control for the possibility that CP-dn-ATF5 kills survivin over-expressing tumor cells by a mechanism apart from its dn-ATF5 activity, we also asked whether survivin over-expression would rescue cells transfected with the pLe-GFP-FLAG-dn-ATF5 plasmid." (PMID 31551409, 2019). "It was found that ATF5 promoter methylation was substantially increased in HCC and that ATF5 knockdown enhanced growth of various HCC cell lines, further supporting the tumor suppressive role of ATF5 in HCC." (PMID 29137451, 2017). "In the present study, the expression patterns of a number of tumor-related classical genes (eg, VEGF, PGF, FGF18, AKT, E2F1, ATF5) within our microarray dataset were detected as predicted." (PMID 22962576, 2012). "If homozygous deletion of the ATF5 gene does not result in embryonic lethality, then crossing ATF5 knock-out mice with mice bearing genetic mutations that induce tumorigenesis would ascertain whether ATF5 is essential for tumor formation and progression in vivo." (PMID 21311102, 2010). "The major aim of this work was to determine whether Dpep, a cell-penetrating peptide that targets the leucine zipper transcription factors ATF5, CEBPB, and CEBPD, could effectively sensitize tumor cells to the cytotoxic actions of NK-92MI cells." (PMID 40358191, 2025). "In GC, H3K18la promotes ATF5 mRNA degradation by increasing METTL14 expression, thereby inhibiting the ATF5-driven transcriptional activation of WDR74 and preventing the nuclear translocation of β-catenin, ultimately suppressing tumor stemness." (PMID 40859309, 2025). "This is especially the case for ATF5, which, as with the more heavily studied ATF4, is subject to selective phospho-eIF2alpha-dependent translation under diverse conditions of cellular stress such as those which tumor cells are likely to encounter in situ." (PMID 36831248, 2023). "Decreased expression of ATF5 in + Dox tumors was verified by immunoblotting, indicating that tumor progression was not due to an escape from ATF5 knockdown." (PMID 38014922, 2023). "ATF5, CEBPB and CEBPD are reported to promote tumor cell migration and metastasis." (PMID 34065488, 2021). "Like ATF5, survivin is highly expressed in multiple tumor types with little expression in most non-transformed cells." (PMID 31551409, 2019). "On the other hand, our experiments indicated that death of tumor cells promoted by CP-dn-ATF5 was not rescued by survivin over-expression." (PMID 31551409, 2019). "Upon a more extensive analysis of RCC cell lines, it was shown that ATF5 expression was not consistently silenced epigenetically, therefore indicating that ATF5 is likely not a putative tumor suppressor in RCC." (PMID 29137451, 2017). "The inability of survivin over-expression to rescue tumor cells from the lethal effects of dn-ATF5 exposure raised the question of whether CP-dn-ATF5 might kill tumor cells by a non-apoptotic mechanism." (PMID 31551409, 2019). "Consequently, the highestextent of apoptosis at the tumour site was induced by ATF5-CaP-rHDL with apercentage of 43%, but almost none in mice treated with NC-CaP-rHDL andATF5-CaP-LNC." (PMID 28489075, 2017).
infection (10 papers, 2013 to 2025). The state of being infected such as from the introduction of a foreign agent such as serum, vaccine, antigenic substance or organism. "Finally, gene expression of activating transcription factor 5 (Atf5) and heat shock protein 10 (Hsp10), mediators of the UPRmt associated with mtROS accumulation (30, –, 33), increased after infection." (PMID 33531400, 2021). "Data concerning the involvement of ATF5 in the viral stress response and its possible role during infections remain sparse." (PMID 38534416, 2024). "ATF5 counteracts infection by Salmonella by inducing innate immunity and the satiety response to prevent any further ingestion of pathogenic bacteria." (PMID 39595547, 2024). "Recently, Salmonella enterica was reported to target ATF5 (an ATFS-1 homolog) to establish infection in mice." (PMID 39595547, 2024). "Here, we show that the mammalian ortholog of ATFS-1, ATF5, protects the host during infection with enteric pathogens but, unexpectedly, by maintaining the integrity of the intestinal barrier." (PMID 36516750, 2022). "We show that ATF5 possesses a conserved role in protecting the host during infection similar to ATFS-1 in C. elegans." (PMID 36516750, 2022). "The PERK branch of UPR-associated genes, including ATF4, ATF5 CHAC1, PDI, and DDIT3, were upregulated upon infection." (PMID 35368019, 2022). "Here, we provide evidence that ATF5/UPRmt defends the mammalian host during infection by enteric pathogens." (PMID 36516750, 2022). "Infection of WT BMDM with M. tuberculosis raised Atf5 mRNA levels 1.6-fold, while this was increased 2.0-fold in Sirt3−/− BMDM." (PMID 33531400, 2021). "Similarly, infection of glioma cells with HCMV induces ATF5 expression at both protein and RNA levels as well as activation of the cellular stress response." (PMID 40622847, 2025). "Whether ATF5 and the UPRmt possess additional functions in other cell types to protect the host during infection would be valuable to explore in future studies." (PMID 36516750, 2022). "We first examined whether ATF5 promotes mitochondrial recovery during infection." (PMID 36516750, 2022). "Thus, a growing number of studies implicate ATF4 and ATF5 in the regulation of the immune response and reveal how the dialogue between stress responses and immune pathways can be fundamental for the regulation of tissue homeostasis by the cell in response to infection." (PMID 38534416, 2024). "We found that, upon infection with S. aureus, ACO2 KD further increased the expression of HSPD1, HSPA9, and CLIPP, three of four selected targets of ATF5, a key mediator of the UPRmt and the mammalian ortholog of C. elegans ATFS-1, in HeLa cells." (PMID 37349299, 2023). "We were intrigued that Atf5ΔIEC mice displayed abnormalities in intestinal structure even in the absence of infection, suggesting that ATF5 promotes intestinal homeostasis under physiological conditions." (PMID 36516750, 2022). "Of these three transcription factors, we have only obtained a DNA binding site for cTf4, which is, like the DNA binding sites of aTf2, aTf5 and aTf7, not enriched among genes up- or down-regulated during infection." (PMID 27855160, 2016). "Interestingly, mitochondrial function was also reduced in Atf5ΔIEC mice in the absence of infection, suggesting that ATF5 possesses activity in the intestine under physiological conditions." (PMID 36516750, 2022). "Remarkably, we also detected some modest abnormalities to gut epithelial integrity in Atf5ΔIEC mice even in the absence of infection, including decreased villi height and increased depth of the intestinal crypts, suggesting that ATF5 promotes gut epithelial homeostasis even under basal conditions." (PMID 36516750, 2022). "Notably, whether ATF5 and the UPRmt possess a similar function as C. elegans ATFS-1 in protecting the host during pathogen infection has yet to be explored." (PMID 36516750, 2022).
metabolic disease (3 papers, 2022 to 2025). A congenital disorder (due to inherited enzyme abnormality) or acquired (due to failure of a metabolically important organ) disorder resulting from an abnormal metabolic process. "Additionally, in metabolic disorders, FGF-21 alleviates mitochondrial stress by regulating the ERK1/2 pathway and modulating activating transcription factor 5 (ATF5) and C-Myc expression." (PMID 40437610, 2025).